PLEC (plectin)
Diseases named in the same sentence as PLEC in open-access papers (continued):
Sharing a sentence is not in itself a finding about the gene and the disease.
skin cancer (2 papers, 2021 to 2024). "During early skin tumor development, integrin α6β4 recruits plectin to the plasma membrane, exerting an inhibitory effect." (PMID 39334817, 2024). "Additional studies are needed to elucidate if the dual role of integrin β4 is related to the suppression of a plectin-dependent anti-proliferative signal in skin cancer." (PMID 34571895, 2021). "In skin cancer, IHC analysis has revealed decreased plectin expression in basal cell carcinoma of the skin and, to a smaller extent, in squamous cell carcinoma and in situ carcinoma compared to adjacent normal tissue." (PMID 34571895, 2021).
stomach cancer (2 papers, 2011 to 2021). "Impressively, plectin expression was higher across multiple tumor samples, including esophageal, ovarian, pancreatic, and stomach carcinomas, all of which have been previously reported as having upregulated plectin protein expression." (PMID 34571895, 2021).
vulvar carcinoma (2 papers, 2016 to 2026). "The effect of plectin downregulation by shRNA was first tested by transient transduction of vulvar carcinoma-derived A431 cells." (PMID 27007410, 2016). "However, other studies reported a modest 10% increase in stiffness upon plectin knockout in mouse keratinocytes and no significant change in vulvar carcinoma cells." (PMID 40913316, 2026).
acute respiratory distress syndrome (1 paper, 2015). Progressive and life-threatening pulmonary distress in the absence of an underlying pulmonary condition, usually following major trauma or surgery. "Our study links the intermediate-filament–plectin complex to an important barrier-protective function, particularly in stress-exposed endothelium, which is likely to be a prime target under endothelial injury conditions such as pulmonary oedema and acute respiratory distress syndrome." (PMID 26519478, 2015).
bullous pemphigoid (1 paper, 2020). Bullous pemphigoid (BP) is the most common form of autoimmune bullous dermatosis. "BP180 acts as a core anchor protein due to its multiple binding sites (i.e., extracellular domains of integrin α6, cytoplasmic domains of integrin β4, laminin-5 and plectin) connecting intra- and extra-cellular hemidesmosomal proteins and playing a role in the development of bullous pemphigoid." (PMID 32210969, 2020).
carcinoma in situ (1 paper, 2021). "Plectin IHC staining of human tissues revealed that a small percentage of early lesions (PanIN I/II) were positive for plectin expression (0–3.85%), while 60% of PanIN III lesions, considered carcinoma in situ, were positive." (PMID 34571895, 2021).
cervical cancer (1 paper, 2021). A primary or metastatic malignant neoplasm involving the cervix. "However, in contrast to other cancers, plectin deficiency in this cervical cancer model increased FAK and Rac1-GTPase activity, cell motility, and enhanced cell migration." (PMID 34571895, 2021). "In vitro suppression of plectin in cervical cancer HeLa (Chang liver) cells resulted in reduced cytokeratin 18 expression, hemidesmosome disassembly, IF disorganization, increased actin-rich stress fibers, and altered cellular morphology." (PMID 34571895, 2021).
cholangiocarcinoma (1 paper, 2025). A carcinoma that arises from the intrahepatic biliary tree (intrahepatic cholangiocarcinoma) or from the junction, or adjacent to the junction, of the right and left hepatic ducts (hilar cholangiocarcinoma). "More interestingly, there are also ongoing studies exploring the diagnostic role of plectin in cholangiocarcinoma obtained by ERCP (Endoscopic Retrograde Cholangiopancreatography) (NCT06651346)." (PMID 41169522, 2025).
cholestasis (1 paper, 2022). Impairment of the bile flow caused by obstruction within the liver, or outside the liver in the bile duct system. "Recent work implies that plectin mediates the cellular response to cholestasis, which provides the biliary epithelium with resilience against increased bile pressure." (PMID 35139142, 2022).
colon adenocarcinoma (1 paper, 2025). "Plectin-1 treatment reduced spheroid growth and decreased the colony-forming ability of colon adenocarcinoma cells." (PMID 41169522, 2025).
colorectal tumors (1 paper, 2025). "Plecstatin can target plectin and inhibit colorectal tumors." (PMID 41169522, 2025).
dysplasia (1 paper, 2017). A usually neoplastic transformation of the cell, associated with altered architectural tissue patterns. "The levels of plectin were significantly higher in OSCCs than in fibrous hyperplasias and dysplasias (p<0.0001)." (PMID 29088820, 2017).
dystrophin deficiency (1 paper, 2013). "The overexpression of plectin in mdx muscle could be seen as a cellular response to dystrophin deficiency that counteracts the compensatory action of upregulated utrophin under these conditions." (PMID 23758845, 2013).
Emery-Dreifuss muscular dystrophy (1 paper, 2024). Emery-Dreifuss muscular dystrophy (EDMD) is characterized by muscular weakness and atrophy, with early joint contractures and cardiomyopathy. "Interestingly, in Emery-Dreifuss Muscular Dystrophy (EDMD2) myoblasts exposed to mechanical stretching, the recruitment of desmin and plectin to the nucleus and nuclear orientation were impaired, suggesting that a functional lamin A/C is crucial for the response to mechanical strain." (PMID 38247853, 2024).
endometrial cancer (1 paper, 2021). Primary or metastatic malignant neoplasm involving the endometrium (mucous membrane that lines the endometrial cavity). "In endometrial cancer, plectin IHC analysis revealed strong plectin expression in malignant tissues with and without lymph node metastasis but only faint staining in normal tissue." (PMID 34571895, 2021).
Fasciola infection (1 paper, 2024). "While the role of plectin in the polarization of macrophages thus remains unclear, the increase in its expression mediated by the host lncRNAs during Fasciola infection could be related to its role in structural cellular processes involving actin filament dynamics, such as phagocytosis and motility." (PMID 39344634, 2024).
femoral neck fracture (1 paper, 2019). Fractures of the short, constricted portion of the thigh bone between the femur head and the trochanters. "Our AEI data indicate that the OA risk–conferring A allele of rs11780978 correlates with reduced expression of PLEC but with increased expression of GRINA, while our RNA‐Seq data revealed increased PLEC expression but decreased GRINA expression, in OA versus non‐OA (femoral neck fracture) cartilage." (PMID 30730609, 2019).
fibrosarcoma (1 paper, 2021). A malignant mesenchymal fibroblastic neoplasm affecting the soft tissue and bone. "Interestingly in fibrosarcoma, proteomic analysis revealed that treatment with a vascular disrupting agent, combretastatin A4-phosphate, reduced plectin expression compared to untreated tumors." (PMID 34571895, 2021). "Likewise, a proteomic and IHC analysis of tumors from a mouse fibrosarcoma model revealed plectin to be abundantly expressed in malignant tissue." (PMID 34571895, 2021).
glomerular diseases (1 paper, 2018). "Taken together, these findings indicated that plectin protects podocytes from ADR‐induced apoptosis and F‐actin cytoskeletal disruption by inhibiting integrin α6β4/FAK/p38 pathway activation and that plectin may be a therapeutic target for podocyte injury‐related glomerular diseases." (PMID 30187999, 2018).
hip osteoarthritis (1 paper, 2025). "In terms of specific genes likely to affect both hip shape and either hip osteoarthritis or fracture, SMAD3 and PLEC were the only genes identified through colocalisation between GWAS signals and mRNA expression in human joint tissue and both were associated with hip osteoarthritis." (PMID 39574169, 2025). "Fine mapping implicated SMAD3 and PLEC as candidate genes that may be involved in the development of hip shape and hip osteoarthritis." (PMID 39574169, 2025).
intraductal papillary mucinous neoplasms (1 paper, 2024). "Also, the research has demonstrated that plectin is a potential biomarker for intraductal papillary mucinous neoplasms (IPMN) of the pancreas, facilitating the differentiation between benign and malignant IPMN." (PMID 39334817, 2024).
kidney cancer (1 paper, 2018). Primary or metastatic malignant neoplasm involving the kidney. "Our study identified that the expression of CD151 downstream genes ITGB1, ITGB4, and PLEC may have additional prognostic values in kidney cancers." (PMID 29843367, 2018).
laminopathies (1 paper, 2024). "Interestingly, as observed for desminopathies and laminopathies, diseases due to mutation of plectin gene (PLEC), may present a phenotype characterized also by muscular dystrophy." (PMID 38247853, 2024).
leukoplakia (1 paper, 2023). A white patch or plaque on a mucous membrane that cannot be characterized clinically or pathologically as any other disease. "Across control, leukoplakia, and cancer, L-lactate dehydrogenase A chain, plectin, and WD repeat-containing protein 1 were upregulated, whereas thioredoxin 1 and spectrin alpha chain, nonerythrocytic 1 were downregulated." (PMID 36776920, 2023).
lymph node metastasis (1 paper, 2015). "For patients without lymph node metastasis (N0), at any T-stage, the risk of dying of the disease within 5 years was significantly decreased in patients with low plectin expressing tumors compared to those with high plectin expression (p = 0.008)." (PMID 26306491, 2015).
mastitis (1 paper, 2025). Inflammation of breast tissue during lactation or postpartum due to an obstructed duct or infection. "The identification of DEGs and potential target genes, particularly PTPRF, DCTN1, PLEC, MYOF, and DPP9, underscores the critical role of miR-223 in modulating mastitis-related traits in dairy cattle." (PMID 40033327, 2025).
meningioma (1 paper, 2023). A generally slow growing tumor attached to the dura mater. "Plectin, a cytoskeleton and cell migration marker, have been observed to be down-regulated in our high grade Meningioma samples." (PMID 37770851, 2023). "However, Plectin (PLEC) and Mucins (MUC4, MUC5A, MUC1) were found to be downregulated in high grade Meningioma." (PMID 37770851, 2023).
neurotoxicity (1 paper, 2022). Toxicity that causes injury to the central or peripheral nervous system or damages its function. "The third module included 3 genes in Neurotoxicity (Itpr1, Trim8, Lrp1), 4 in Blood–brain barrier (Ptpn23, Claudin5, Plectin, Mmp2) and 4 in Cognitive function (Slc8a3, Srf, Nf1, Ncam1)." (PMID 35899365, 2022).
oral cancer (1 paper, 2017). "With the exception of this study, little has been uncovered regarding the biological mechanisms related to plectin in oral cancer." (PMID 29088820, 2017). "Subsequent immunohistochemical analysis of specimens representing OSCC development revealed that fascin levels were already significantly upregulated in mild dysplasias, keeping higher levels throughout oral cancer progression, whereas plectin upregulation was detected only in cancer areas." (PMID 29088820, 2017).
osteoporosis (1 paper, 2023). A condition of reduced bone mass, with decreased cortical thickness and a decrease in the number and size of the trabeculae of cancellous bone (but normal chemical composition), resulting in increased fracture incidence. "Although various causes have been reported to induce osteoporosis in this disease, the underlying biological mechanism by which PLEC mutations affect bone metabolism is unclear, and future studies are expected to elucidate this mechanism." (PMID 37461309, 2023).
ovarian tumours (1 paper, 2024). "In conclusion, this study found significantly lower expression levels of the plakins, PLEC and PPL, in Type II compared to Type I ovarian tumours." (PMID 39682273, 2024).
pancreatic adenocarcinoma (1 paper, 2025). "PLEC has been identified as a promising biomarker and therapeutic target in pancreatic adenocarcinoma (PAAD), while amplification of NSB1 has been shown to drive the pathobiology of uveal melanoma (UM)." (PMID 41287790, 2025).
pemphigoid (1 paper, 2021). "For the correct assembly of the cytoplasmic parts of HDs, the binding of type XVII collagen to the bullous pemphigoid antigen-230 and plectin is required." (PMID 33805154, 2021).
respiratory infection (1 paper, 2022). "One of the two patients of family 10 (PT17), who had compound heterozygous mutations (c.5269C > T and c.6067delG in PLEC), died of respiratory infection." (PMID 36578049, 2022).
schizophrenia (1 paper, 2023). A major psychotic disorder characterized by abnormalities in the perception or expression of reality. "Among highly ranked genes lacking SFARI Gene scores and OMIM annotations, previous studies suggest association with NDDs and schizophrenia [OBSCN, PLEC, RYR2, ZSWIM8], cortical formation and thickness [LAMA5, GOLGA3), and neurodegenerative diseases (PKHD1, DNAH1]." (PMID 35596027, 2023).
serous carcinoma (1 paper, 2021). "Moreover, an analysis of the differential expression levels of plectin mRNA between serous carcinoma and normal tissue via Oncomine revealed that plectin mRNA is significantly overexpressed in serous ovarian cancer tissues." (PMID 34571866, 2021).
serous ovarian tumors (1 paper, 2025). "COL12A1, PLEC, and SLC4A1 expression levels were significantly increased in serous ovarian tumors (grade 3) that did not respond to platinum and taxane chemotherapy compared to responders after 6 months of treatment." (PMID 40565351, 2025).
cancer (72 papers, 2011 to 2025). A tumor composed of atypical neoplastic, often pleomorphic cells that invade other tissues. "Although plectin deficiency is known to cause tissue disorders, a clearer understanding of plectin dysregulation and its implications in cancer is still necessary." (PMID 41011568, 2025). "The aberrant localization of plectin on the cell surface is closely associated with enhanced invasive and metastatic potential in cancer cells." (PMID 41011568, 2025). "Taken together, our proteomic analyses suggest a regulatory role for plectin in the mechanosensitive, cell adhesion-linked signaling which is critical for cancer development and dissemination." (PMID 40052672, 2025). "For instance, high levels of plectin have been associated with prostate cancer, regulating cancer growth and metastasis, while the inhibition of periplakin in pharyngeal squamous cancer cells reduces cellular movement and adhesion." (PMID 39052015, 2024). "Second, research has reported that integrin α6β4 plays a dual role in epidermal tumors, either inhibiting or promoting cancer, and this is associated with plectin." (PMID 39334817, 2024). "Here, we review the current understanding of plectin’s critical role in cancer biology, its diagnostic capabilities, and its therapeutic potential, all of which underscore its far-reaching biologic significance and clinical utility." (PMID 34571895, 2021). "Here, we report on plectin’s differential gene and protein expression in cancer, explore its mutational profile, and discuss the current understanding of plectin’s and CSP’s biological function in cancer." (PMID 34571895, 2021). "To further examine plectin’s mutation profile, we analyzed 10,967 samples spanning 32 The Cancer Genome Atlas (TCGA) cancer types from their PanCancer Atlas datasets using cBioPortal, of which 5.1% had somatic mutations." (PMID 34571895, 2021). "Expression of plectin appears higher in cancer tissue and plectin-deficiency can result in higher migration." (PMID 31819039, 2019). "This is consistent with the role of Plectin in association with vimentin in providing a scaffold for invadopodia, facilitating cancer cell invasion and metastasis." (PMID 27470985, 2016). "The in situ immunohistochemical data suggests a possible correlation between the higher FAK activation and the invasiveness of cancer cells with plectin deficiency." (PMID 25774093, 2015). "Likewise, the virus-encoded artificial microRNA amiR-4 reduces plectin expression and enhances the cytotoxicity of cancer cells, highlighting the potential of RNA-based therapeutics in oncology." (PMID 41011568, 2025). "First, the association of plectin expression with overall survival varies across multiple cancers." (PMID 39334817, 2024). "α6β4-integrins and plectin are the key structural components of hemidesmosomes that have been implicated in carcinogenesis and which are thus considered as potential cancer biomarkers and drug targets for anti-cancer therapies." (PMID 36612146, 2022). "In addition, researchers have linked aberrant expression of plectin to cancer cell migration and invasion, but the underlying molecular mechanisms remain largely unaddressed." (PMID 36613521, 2022). "Further support that plectin regulates cancer cell survival comes from loss of function studies." (PMID 34571895, 2021). "Interestingly, it is not only plectin’s expression or mutation status but also localization that is altered in cancer." (PMID 34571895, 2021). "Moreover, plectin was found to be altered in 11% (1158/10,950) of TCGA pan-cancer samples, with amplification and missense mutations being the most common genetic alterations." (PMID 34571895, 2021). "Importantly, multiple studies have shown plectin expression to be associated with cancer progression and metastasis." (PMID 31628412, 2019).